BRAF (B-Raf proto-oncogene, serine/threonine kinase)
Diseases named in the same sentence as BRAF in open-access papers (continued):
Sharing a sentence is not in itself a finding about the gene and the disease.
melanoma (continued). "The third reported strategy is based on the success of the approved and emerging therapies targeting the BRAF/MAPK signaling in melanoma." (PMID 25763355, 2015). "RAF or MEK inhibitors inhibit ERK phosphorylation (P-ERK) and induce BIM levels in BRAF-mutant melanoma cell lines." (PMID 26639561, 2015). "Wild type A375 and SK-MEL-28 melanoma cells completely lost sensitivity to BRAF inhibitors alone or in combination with MEK1/2 inhibitors upon Mcl-1 overexpression and transformed them into resistant cells." (PMID 26497853, 2015). "In melanoma, coding mutations in the mitogen-activated kinase pathway (MAPK) (e.g., BRAF and RAS) are common and contribute to disease severity." (PMID 26029660, 2015). "In this real-life study, we evaluated the concordance of the cobas 4800 BRAF V600 Mutation Test relative to the home brew methods (HBM) used at 12 participating INCa platforms when tested in parallel for BRAF genotyping in melanoma samples." (PMID 25789737, 2015). "It has also been shown that BRAF triggers MITF expression in melanoma cells by inhibiting Brn-2, a transcription factor." (PMID 26393652, 2015). "Taken together, these results indicate that the combination of I-BET151 and LBH589 synergistically induces apoptosis and cell cycle arrest in melanoma, even in cells with acquired resistance to BRAF inhibitors." (PMID 26087189, 2015). "For patients with activated BRAF pathways in their thyroid tissues, knowledge on molecular medicine of the BRAF cascade in melanoma becomes highly valuable." (PMID 25600636, 2015). "The National Comprehensive Cancer Network (NCCN) guidelines currently recommend pembrolizumab, nivolumab, ipilimumab, or high-dose IL-2 for first-line therapy for metastatic or unresectable BRAF V600 wild-type melanoma." (PMID 26557410, 2015). "The group of 495 previously untreated patients with BRAF V600-positive melanoma was randomized into vemurafenib plus cobimetinib and vemurafenib and placebo arms." (PMID 26171394, 2015). "Rapid and dramatic responses have been observed with oncogene-directed treatments, such as BRAF inhibitors in melanoma and epidermal growth factor receptor (EGFR) inhibitors in non-small cell lung cancer." (PMID 25682878, 2015). "BRAF mutant (V600E) melanoma and thyroid cancers are sensitive, but colon cancers are resistant to therapy with vemurafenib (FDA approved drug)." (PMID 26643872, 2015). "We used a set of biopsies from four patients with BRAFV600E-mutant melanoma, where for each patient, samples before and after vemurafenib (a clinical BRAF inhibitor) treatment, as well as matching normal references, are available." (PMID 25887352, 2015). "In melanomas, the MAPK pathway is frequently hyperactivated by mutations in the BRAF gene (approximately 50% of melanomas) but also in NRAS (18%), KIT (9%), HRAS (2%) or KRAS (2%) genes (COSMIC database)." (PMID 26098773, 2015). "PLX4032 treatment also increased RHOB protein level in six other BRAF-mutant melanoma cell lines, which are representative of melanoma progression (RGP-VGP to metastatic)." (PMID 26098773, 2015). "Given the significance of BRAF activation in melanoma cells, the down-regulation of BRAF in the DW-F5-treated cells and xenograft tissues assumes importance." (PMID 26061820, 2015). "We previously showed that IGF-1R depletion blocks survival of BRAF mutant and wild-type (WT) melanoma cells, and enhances chemosensitivity." (PMID 26497996, 2015). "Of the 349 tumors, 148 harbored T1799A mutation (p.V600E) of the BRAF gene by both Sanger sequencing and Cobas 4800 BRAF V600 Mutation Test, including 38 cases of CRC, 100 cases of PTC and 10 cases of malignant melanoma." (PMID 25784606, 2015). "MEK inhibitors, which have achieved significant success in the treatment of BRAF mutant melanoma, have been less effective as single agents in early clinical trials of both unselected and KRAS mutant colorectal cancer patients." (PMID 26136684, 2015).
melanoma (continued). "Additional interest in the expression of PD-L1 on melanoma was generated by the observation that PD-L1 was up-regulated on melanoma cells that had become resistant to treatment with selective BRAF V600 inhibitors." (PMID 25844720, 2015). "SOX2 was also not induced in other oncogene-dependentmodels, such as ALK-translocated lung cancer cells treated withcrizotinib, HER2-amplified breast cancer cells exposed to lapatinibor BRAF-mutant melanoma cells treated with AZD6244." (PMID 25686219, 2015). "Here, we show that, in BRAF-mutant melanoma cells, inhibition of BRAF or its target MEK induces RHOB expression by a mechanism that depends on the transcription factor c-Jun." (PMID 26098773, 2015). "BRAFV600-mutant melanomas are exquisitely sensitive to BRAF inhibitors such as dabrafenib and vemurafenib, which alone or in combination with a MEK inhibitor improve the overall survival of BRAFV600-mutant melanoma patients." (PMID 26524482, 2015). "Treatment options for malignant melanoma patients are limited, as metastatic melanoma easily becomes resistant to therapies (such as resistance to BRAF inhibitors, BRAFi)." (PMID 26393652, 2015). "In RAF-inhibitor resistant melanoma cells, we measured 143 proteomic/phenotypic entities under 89 perturbation conditions and predicted c-Myc as an effective therapeutic co-target with BRAF or MEK." (PMID 26284497, 2015). "We believe that this approach would better reflect the limitation of BRAF testing in melanoma including the fact that we usually handle FFPE specimens with a variable percentage of cancer cells and often showing a marked intratumour heterogeneneity." (PMID 26690267, 2015). "In vitro and in vivo assays confirmed the selective expression of the corresponding proteins in BRAFV600E cell lines derived from primary and metastatic melanoma lesions or in BRAF mutant tumors compared to BRAF wild type tumors and nevi." (PMID 25576923, 2015). "Neuroblastoma v-ras oncogene homolog (NRAS) and v-raf murine sarcoma viral oncogene homolog B1 (BRAF) are oncogenes in melanoma, which are critical for tumor initiation." (PMID 26095858, 2015). "The Cu-dependency of MEK1/2 becomes exposed when the MAPK pathway is driven by activating mutations in BRAF, and under these circumstances treatment with the Cu chelator TTM reduces the growth of human melanoma xenografts." (PMID 26155939, 2015). "We tested the method on a small cohort of BRAF V600E positive melanoma patients of varying tumor stages." (PMID 26562020, 2015). "Recent data from melanoma further support this important role in BRAF mediated transformation, as MIG-6 dephosphorylation was associated with EGFR activation and resistance to BRAF inhibitors." (PMID 26065894, 2015). "The growth of the BRAF V600E mutant 518A2 melanoma cells and M14 melanoma cells treated with 1 μM vemurafenib was inhibited by 40±3% and 60±5%, respectively (data not shown)." (PMID 25997619, 2015). "A good correlation has already been described between anti-BRAFV600E IHC and ultra-deep sequencing of BRAF in colorectal carcinomas and in melanomas." (PMID 26204954, 2015). "Taken together, this data suggests that Wnt pathway activation is a potential therapeutic strategy in patients with BRAF wild type or BRAF mutant melanoma." (PMID 25915038, 2015). "For example, EGF signaling confers resistance to BRAF inhibition and induces melanoma invasion through Src pathways." (PMID 25763355, 2015). "Thirty-five patients had concordantly BRAF-positive and 36 (48%) patients had concordantly BRAF-negative primary melanomas and matched metastases, and four patients had discordant samples with low allele frequencies (3.4–5.2%)." (PMID 26498143, 2015). "The BRAF mutation in melanoma drives enhanced proliferation through MAPK-induced expression of cyclin D1 and mediates BRAF inhibitor resistance in melanoma cells." (PMID 26299806, 2015).
melanoma (continued). "Recently, the combined use of BRAF and MEK inhibition has become a new standard for inhibiting the MAPK pathway in patients with advanced BRAF mutant melanoma." (PMID 26640950, 2015). "Among the 779 cases, 150 cases were positive for BRAF (V600E) staining, including 38 (of 611, 6%) CRCs, 102 (of 127, 80%) PTCs and 10 (of 41, 24%) malignant melanomas." (PMID 25784606, 2015). "An impressive example is the contradictory efficacy of BRAF inhibitors in patients with melanoma versus patients with CRC." (PMID 26617477, 2015). "Mutations in BRAF are known to negatively impact anti-EGFR therapy in colorectal cancer but have a beneficial effect in melanoma in response to the use of BRAF/MEK inhibitors." (PMID 26315110, 2015). "Three qPCR assays were tested with spike-in experiments, specific for point mutations BRAF V600E, PTEN T167A and NRAS Q61L of melanoma cell lines." (PMID 26562020, 2015). "Silencing of Mcl-1 using siRNA completely sensitized resistant melanoma cells to growth suppression and induction of apoptosis by BRAF inhibitors." (PMID 26497853, 2015). "It is noteworthy that melanoma cells with acquired resistance to BRAF inhibitors (BRAFi) maintain an OXPHOS phenotype regardless of the underlying resistance mechanism." (PMID 26713093, 2015). "As single agents, dabrafenib and trametinib are potent inhibitors of the proliferation of the BRAF-mutant A375 melanoma cell line, with IC50 of 26 nM and 19 nM, respectively." (PMID 26018524, 2015). "Constitutive activation of AKT protects cells from BRAF inhibitors, and detection of elevated AKT phosphorylation in BRAF-inhibitor-resistant melanoma cells suggests that enhanced AKT levels are associated with BRAF-inhibitor-ineffectiveness." (PMID 26299806, 2015). "Hypoxia induced switching of the expression of ROR1 and ROR2 through non-canonical WNT5A signaling, resulting in an invasive phenotype of melanoma with reduced sensitivity to BRAF inhibitors." (PMID 25763355, 2015). "Of particular interest, SGK3 has recently been reported to contribute to the growth of mutant BRAF melanomas." (PMID 26573229, 2015). "The prolonged survival in our patient with BRAF inhibitor-based therapy is very encouraging for the management of patients with melanoma and LMD." (PMID 25962795, 2015). "All patients had disease progression after at least two doses of ipilimumab, and patients with BRAF-mutant melanoma were required to have previous treatment with at least one of the BRAF or MEK inhibitors (vemurafenib, dabrafenib, or trametinib)." (PMID 26557410, 2015). "The response of BRAF-mutant melanoma patients to BRAF inhibitors is dramatically impaired by secondary resistances and rapid relapse." (PMID 26098773, 2015). "In this study, we have established that resistance to BRAF inhibitors such as vemurafenib or dabrafenib alone or in combination with MEK1/2 inhibitor (trametinib) in melanoma cells was due to overexpression of Mcl-1." (PMID 26497853, 2015). "Further studies will be required to establish the potential role of BRAF induced clastogenesis and BRAF induced UVB sensitivity to the progression of melanoma from nevi." (PMID 26091525, 2015). "Our study demonstrated that IHC would be a useful tool for BRAF mutation screening in CRC, PTC and melanoma and potentially other tumor types." (PMID 25784606, 2015). "In human non-melanoma malignancies, the therapeutic efficacy of BRAF inhibitors is highly variable between different types of cancer, despite the presence of the BRAFV600E mutation." (PMID 29061943, 2015). "For example, the median PFS of BRAF inhibitors in BRAFV600E/K mutant melanoma ranges from 5–8 months." (PMID 25682878, 2015).
melanoma (continued). "BAY 87-2243 significantly reduced tumor growth in various BRAF mutant melanoma mouse xenografts and patient-derived melanoma mouse models." (PMID 26500770, 2015). "Most relevant to this study, oncogenic BRAF mutants have been shown to down-regulate the expression of axonal guidance genes in melanoma." (PMID 25671303, 2015). "We next determined the effects of fisetin, sorafenib and their combination on an in vivo xenograft mouse model subcutaneously implanted with BRAF-mutated A375 and SK-MEL-28 melanoma cells." (PMID 26299806, 2015). "A total of ten patients with BRAF-mutant, advanced melanoma who had achieved a PR or CR on a BRAF and/or MEK targeted drug were analyzed for molecular alterations." (PMID 25886620, 2015). "Taken together, we showed that mitochondrial ATF2 is involved in the induction of apoptosis and BRAF inhibitor resistance in some melanoma cell lines." (PMID 26462148, 2015). "Loss of MED12, a repressor of TGF–βR2 signaling, not only confers a mesenchymal phenotype, but also results in resistance to inhibitors of ALK, EGFR, and BRAF in multiple cancers including melanoma." (PMID 25763355, 2015). "PlexinA2 and PlexinA4, known Sema6A receptors, showed differential expression in BRAF-mutant clones and melanomas, indicating that in such tumors only Plexin-A4 acted as Sema6A receptor." (PMID 25576923, 2015). "All the melanoma cell lines tested in the present study were highly sensitive to the treatment with BRAF inhibitors (vemurafenib and dabrafenib) alone or in combination with MEK1/2 inhibitor (trametinib)." (PMID 26497853, 2015). "We found 202,968 unique relationships linking BRAF inhibitor drugs to 30 out of 39 non-BRAF inhibitor melanoma drugs that were indexed in DrugBank." (PMID 26262134, 2015). "Professor Jeffrey Sosman from the Vanderbilt University Medical Center in Nashville (USA), focused on BRAF wild type melanomas." (PMID 25932043, 2015). "With the epidemiological link between oncogenic BRAF(V600E) and melanoma being well established, the contribution of BRAF(V600E) to melanoma development is under intense investigation." (PMID 26091525, 2015). "Melanoma cells resistant to BRAF inhibitors showed massive expression of Mcl-1 as compared to respective sensitive cell lines." (PMID 26497853, 2015). "Here, we confirm previous findings that melanoma cells adapt to BRAF inhibitors by upregulating OXPHOS therefore validating our approach to effectively target this pathway with the selective mitochondrial complex I inhibitor BAY 87-2243." (PMID 26500770, 2015). "Altogether thirteen human melanoma cell lines with different NRAS, BRAF and PTEN mutational status were treated with the prenylation inhibitor zoledronic acid (ZA)." (PMID 25646931, 2015). "Immunotherapy is significantly improving long-term survival in a subset ofmelanoma patients, and new drugs, particularlythose that target mutant BRAF found in about 50% of melanoma, have provided some hope,but resistance and relapse are typically encountered." (PMID 25749035, 2015). "Ipilimumab’s mechanism of action is therefore fundamentally different from other conventional melanoma (and cancer) treatments (including BRAF inhibitors), which is reflected in the unusual survival profile discussed in this paper." (PMID 26700304, 2015). "Among gene products that operate downstream of the signal transduction BRAF–MEK–ERK pathway, the microphthalmia-associated transcription factor (MITF) seems to play the most relevant role in melanoma." (PMID 26322273, 2015). "Non-small cell lung cancer and melanoma are at the forefront of molecular diagnostics, with a variety of treatments targeting molecular alterations defining specific cancer subtypes (e.g., BRAF, EGFR, ALK alterations)." (PMID 25720744, 2015).
melanoma (continued). "Despite these therapeutic advances approximately 50% of melanoma patients treated with BRAF and MEK inhibitors will progress within 12 months." (PMID 26524482, 2015). "Targeting mutated BRAF, and consequently shutting down the MAPK signaling pathway, has been directly translated into therapeutic management in melanoma." (PMID 25784655, 2015). "Among these included the HDAC inhibitor vorinostat, recently found to synergize with BRAF inhibitors in some melanoma cell lines." (PMID 26461489, 2015). "With the many available active anti-melanoma agents, the optimal treatment algorithm for various subsets of patients, e.g. BRAF mutants, NRAS mutants, PD-1 expressing, has yet to be determined." (PMID 27508107, 2015). "The activation of the PI3K–AKT pathway also represents one of the main mechanisms of resistance to MEK inhibitors in BRAF-mutant melanomas." (PMID 26322273, 2015). "Most importantly, the present study has used the fully automated IHC method to detect BRAF V600E mutation in various carcinomas including CRC, PTC and melanoma." (PMID 25784606, 2015). "Second, freshly isolated melanocytes (MELANOMA17 cells hereafter) were also inspected for the presence of mutations of BRAF and ERK5 and for the expression of well-known melanoma markers such as S100A and MCSP." (PMID 26327537, 2015). "The pre-treatment tumor displayed a relatively low-level phosphorylation of ERK, but higher than seen in control skin, in agreement with the observation that this concerned a BRAF mutant melanoma." (PMID 26105199, 2015). "BRAF V600E PDA cell line was equally sensitive as MNT1 melanoma cells to the FDA-approved BRAF inhibitor PLX-4032, while KRAS driven cells (PL45) are resistant." (PMID 25855536, 2015). "In order to better understand response and resistance, we analyzed patients with BRAF -mutant, advanced melanoma who achieved a PR or CR on a BRAF and/or MEK targeted agent." (PMID 25886620, 2015). "This phenomenon of increased TAPP expression has been reported in melanoma cell lines when a BRAF inhibitor (vemurafenib) is administered." (PMID 26175925, 2015). "Loss of NF1 function, a well-known tumour-suppressor gene in melanoma, has been implicated on multiple occasions in resistance to PLX4032 targeted therapies in BRAF-mutant melanoma." (PMID 25980496, 2015). "As for the remaining cohorts, 30 and 41 patients with NRAS- and BRAF-mutant melanomas, respectively, received MEK162 45 mg twice daily." (PMID 26171394, 2015). "Approximately 40–50% of melanomas harbour activating mutations in the RAS-RAF axis, commonly V600E BRAF." (PMID 26497996, 2015). "Most melanomas display aberrant activation of the mitogen activated protein kinase (MAPK) pathway, most frequently via oncogenic mutations affecting BRAF and NRAS." (PMID 26524482, 2015). "The clinical significance of EGFR expression was examined in ten surgical specimens of five patients with BRAF-mutant melanomas treated at our Institute with the BRAFi Vemurafenib." (PMID 25742786, 2015). "Targeted therapeutics that suppress melanoma growth such as BRAF inhibitors Vemurafenib or Dabrafenib, or the direct MEK inhibitors Cobimetinib or Tranetinib, have revolutionized metastatic melanoma therapy and have at last improved patient survival." (PMID 26355347, 2015). "Our data demonstrated that fisetin also induces apoptosis in melanoma cells by cleavage of caspase-3 and PARP, and modulation of expression of the Bcl2 family of proteins in BRAF-mutated melanoma cells." (PMID 26299806, 2015). "Recently, two cases of LMD from BRAF V600E-mutant melanoma have shown clinical responses to vemurafenib-containing treatment." (PMID 25962795, 2015). "In the present study, we demonstrated that BRAF-V600E evoked RSK-mediated EphA2 phosphorylation in melanoma cells." (PMID 26158630, 2015).